PDGFRB (platelet derived growth factor receptor beta)
Diseases named in the same sentence as PDGFRB in open-access papers (continued):
Sharing a sentence is not in itself a finding about the gene and the disease.
eosinophilia (continued). "PDGFRB gene rearrangement cases typically present as MPNs which are almost always accompanied with eosinophilia." (PMID 22356850, 2012). "Patients with PDGFRB translocations may lack eosinophilia, only low grade in this case, and rarely present with additional cytogenetic or molecular abnormalities." (PMID 41278291, 2025). "The morphologic features of PDGFRB-related disease are variable but are often those of chronic myelomonocytic leukemia, aCML, or chronic myeloproliferative disease with prominent peripheral-blood eosinophilia." (PMID 38337573, 2024). "Clonal eosinophilia is classified into two categories depending on whether there is a molecular rearrangement of the PDGFRA, PDGFRB, or FGFR1 genes, which are responsible for encoding the tyrosine kinase receptors that aid in eosinophil growth." (PMID 39301376, 2024). "However, to date, only imatinib has been approved as a first-line treatment for patients with myeloid disease, with eosinophilia expressing FIP1L1-PDGFRα or carrying other PDGFRα or PDGFRβ fusions." (PMID 33418988, 2021). "Forpatients with myeloid neoplasms (usually myelodysplastic syndrome/myeloproliferativeneoplasms) with eosinophilia and rearranged PDGFRB, the recommendedimatinib dose is 400 mg daily, which reflects the dose consistently used in severalcase series with excellent outcomes." (PMID 30241197, 2018). "In addition, chromosomal aberrations of FGFR and PDGFRB, point mutations in PDFGRA, and T-cell clonality have been identified in rare cases of primary eosinophilia." (PMID 26497854, 2015). "PDGFRB is a frequent target of chromosomal translocations in a subgroup of hematological malignancies recognized in the 2017 World Health Organization (WHO) as a stand-alone category under “Myeloproliferative neoplasms with eosinophilia and gene rearrangement” [2." (PMID 34859285, 2022). "The patient was diagnosed with myeloid/lymphoid neoplasms with eosinophilia and MPRIP::PDGFRB rearrangement in the chronic-phase disease and was initiated on oral imatinib at a daily dose of 100 mg." (PMID 40621131, 2025). "Myeloid or lymphoid neoplasms with eosinophilia can demonstrate gene rearrangements in PDGFRA, PDGFRB, FGFR1, JAK2, or FLT3 or ETV6::ABL or other tyrosine kinase gene fusion (MLN-TK)." (PMID 38611061, 2024). "Some extremely rare fusion genes, such as CSNK2A1::PDGFRB, CBFB::MYH11, and NSD3::NUTM1, have been identified in patients with eosinophilia using RNA−seq techniques." (PMID 38992589, 2024). "Crucial differential diagnoses of Ph− MPN are the category of myeloid/lymphoid neoplasms with eosinophilia and gene rearrangement of PDGFRA, PDGFRB or FGFR1, or with PCM1-JAK2, and myelodysplastic/myeloproliferative neoplasms (MDS/MPN)." (PMID 34298741, 2021). "Atypical mast cell proliferations or aggregates have been reported in myeloid neoplasms with prominent eosinophilia and abnormalities of PDGFRA or PDGFRB." (PMID 27648315, 2016). "Previously it has been found that mast cells harbor PDGFRA rearrangements in cases of myeloid and lymphoid neoplasms with eosinophilia and abnormalities in PDFGRA, PDGFRB, or FGFR1." (PMID 27648315, 2016). "A separate category has been made for myeloid and lymphoid neoplasms with eosinophilia and abnormalities of PDGFRA, PDGFRB, or FGFR1." (PMID 24764730, 2014). "In 2008 WHO classification, a new class of hematopoietic diseases, myeloid and lymphoid neoplasms with eosinophilia and abnormalities in PDGFRA, PDGFRB and FGFR1 genes, were introduced." (PMID 22356850, 2012). "In 2008, a new class of hematopoietic system disorders, myeloid and lymphoid neoplasms with eosinophilia and abnormalities in PDGFRA, PDGFRB and FGFR1 genes, was created by WHO." (PMID 22356850, 2012). "The frequency of eosinophilia varied significantly depending on the specific fusion gene involved: it was present in 91% of patients with FIP1L1::PDGFRA and 100% with ETV6::ABL1, but only in 43% of those with PDGFRB, FGFR1, or JAK2 fusion genes." (PMID 41530508, 2026).
eosinophilia (continued). "While patients with PDGFRA and PDGFRB fusion genes, who are receiving imatinib treatment, generally have a favorable prognosis, the advent of FGFR1 inhibitors offers hope for individuals with clonal eosinophilia and FGFR1 fusion genes." (PMID 39037514, 2024). "Besides eosinophilia, patients often present with monocytosis and an elevated serum tryptase, particularly in cases with PDGFRA or PDGFRB fusion genes." (PMID 39037514, 2024). "If either PDGFRA, PDGFRB, FGFR1, or JAK2::PCM1 gene rearrangement is identified, the diagnosis should be classified as “myeloid or lymphoid neoplasms with eosinophilia and tyrosine kinase gene fusions”; eosinophilia may be a clue to this alternative diagnosis." (PMID 38067330, 2023). "This category name has changed from the previous “myeloid/lymphoid neoplasms with eosinophilia and rearrangement of PDGFRA, PDGFRB or FGFR1, or with PCM1::JAK2” (MLN-eo), to specify the underlying molecular genetic changes and to include cases with ETV6::ABL1, FLT3 fusions or other TK fusion genes." (PMID 37454239, 2023). "In contrast, it was only observed in 13/30 (43%) patients with PDGFRB, FGFR1 or JAK2 fusion genes Absence of eosinophilia was restricted to 9/30 (30%) patients with PDGFRB, FGFR1 and JAK2 fusion genes." (PMID 37454239, 2023). "Myeloid/lymphoid neoplasm with eosinophilia was excluded due to the absence of eosinophilia and lack of mutations in PDGFRA, PDGFRB, FGFR1, or PCM1-JAK2 gene rearrangement." (PMID 35228982, 2022). "Rarely, PDGFRβ rearrangements are cryptic, even if patients with this anomaly (involving over 30 gene fusion partners) can present a disease without eosinophilia." (PMID 33418988, 2021). "Evidence about genetic mutations/rearrangements causing eosinophil expansion is maturing with the recognition of a new specific World Health Organization category, named “Myeloid/lymphoid neoplasms with eosinophilia and rearrangement of PDGFRA, PDGFRB, or FGFR1, or with PCM1-JAK2”." (PMID 29619379, 2018). "Rearrangements of the platelet-derived growth factor receptor alpha (PDGFRA) gene, of the platelet-derived growth factor receptor beta (PDGFRB) gene and the fibroblast growth factor receptor 1 (FGR1) gene or PCM1-JAK2 fusions must be excluded if eosinophilia is present." (PMID 29383443, 2018). "Such TKFs characterize a group of hematological disorders, sharing similar clinico-pathological features, such as peripheral blood eosinophilia, clinical presentation as MPN and/or lymphoid tumors, and, at least for PDGFRα and PDGFRβ fusions, good response to Imatinib." (PMID 26943776, 2016). "Herein, we report the case of a 73-year-old male with acute myeloid leukemia arising from MDS, negative for PDGFRA and PDGFRB, positive for bone marrow eosinophilia, rash, and marked fluid retention, which improved dramatically with imatinib therapy." (PMID 27570624, 2016). "Clonal eosinophilia is associated with myeloid or lymphoid neoplasms harboring PDGFRA, PDGFRB, or FGFR1 rearrangements, Philadelphia-negative myeloproliferative neoplasms, acute myeloid leukaemia, and B- or T-lymphoblastic leukemia/lymphoma featuring marked eosinophilia." (PMID 41552084, 2025). "After ruling out the hypothesis of non−hematologic origin, testing for gene rearrangements associated with clonal eosinophilia, such as BCR::ABL1, PDGFRA, PDGFRB, FGFR1, PCM1::JAK2, and JAK2::V617F, did not yield any definitive clues." (PMID 38992589, 2024). "Fip1-like 1-platelet-derived growth factor receptor alpha and platelet-derived growth factor receptor beta 5q33 translocations, which are genetic abnormalities indicative of myeloproliferation, were negative in this case; moreover, no findings of neoplastic eosinophilia were observed." (PMID 37543825, 2023). "If these translocations are negative, there is peripheral eosinophilia, or there is a history of leukocytosis with eosinophilia, we recommend FISH for ETV6-ABL1, FIP1L1-PDGFRA, PDGFRB, or FGFR1 rearrangements." (PMID 38337573, 2024).
eosinophilia (continued). "Nearly 100 different TK fusion genes, involving at least six TK (PDGFRA, PDGFRB, FGFR1, JAK2, ABL1, FLT3), have been identified in distinct MLN with or without eosinophilia." (PMID 39037514, 2024). "To date, more than 70 different TK fusion genes with recurrent involvement of at least six TK (PDGFRA, PDGFRB, FGFR1, JAK2, ABL1, FLT3) have been identified in clinically and morphologically distinct MLN with or without eosinophilia." (PMID 37454239, 2023). "In 81/135 (60%) evaluable patients, hypereosinophilia (>1.5 × 109/l) was observed in 40/44 (91%) FIP1L1::PDGFRA and 7/7 (100%) ETV6::ABL1 positive patients but only in 13/30 (43%) patients with PDGFRB, FGFR1, and JAK2 fusion genes while 9/30 (30%) patients had no eosinophilia." (PMID 37454239, 2023).
prostate carcinoma (56 papers, 2006 to 2026). A carcinoma that arises from epithelial cells of the prostate gland. "In breast, colon, pancreas and prostate cancers, the high stromal expression of the PDGFRβ protein has been associated with poor prognosis, however its prognostic relevance in tumors of epithelial origin is inconclusive." (PMID 36131239, 2022). "In recent years, both PDGF as well as PDGFRB have been implicated in cancer progression, including prostate cancer." (PMID 24626295, 2014). "The few patients (7%) with low tumor Cav-1 and high tumor PDGFRβ had an approximately 3-fold excess risk of prostate cancer death compared to the added separate relative risks for patients identified as having low tumor Cav-1, or high tumor PDGFRβ respectively (interaction analysis P <0.001)." (PMID 27764093, 2016). "PDGFRB and its oncogenic functions, prognostic value and inhibition have been studied widely in prostate cancer and other cancers." (PMID 36809527, 2023). "Cell Senescence caused the differential expression of six genes belonging to the KEGG Pathway Prostate Cancer (PDGFRB, PDGFRA, CCNE2, E2F2, EGFR and ZEB1)." (PMID 35205253, 2022). "PDGFRβ has also been shown to be expressed on stromal cells that support neo-angiogenic vessels in solid tumors, such as small cell lung cancer and prostate cancer and our study also demonstrated PDGFRβ in the stroma of both PDXs." (PMID 31565187, 2019). "For prostate cancer, PDGFRB (1st) is a growth factor whose signaling inhibition has been shown to induce apoptosis in metastatic prostate cancer cells." (PMID 29017547, 2017). "Since Cav-1 and PDGFRβ in tumor stroma appears to be unrelated but both add prognostic information about prostate cancer clinical outcome a combined variable between the two was constructed and analysed by Cox regression." (PMID 27764093, 2016). "Similarly, increased levels of PDGFRβ and Hyaluronan in prostate tumor stroma and surrounding non-malignant stroma associates with poor outcome of prostate cancer patients and injection of hyaluronan in the prostate increase prostate cancer growth in an orthotopic rat model." (PMID 24505269, 2014). "Preclinical studies have demonstrated potential benefit of inhibition of PDGFRβ signaling by imatinib in prostate cancer." (PMID 24359404, 2013). "Immunohistochemical stainings have revealed that PDGFRβ is upregulated in most primary and metastatic prostate cancer cells." (PMID 24359404, 2013). "PDGFRβ expression was analyzed in normal and tumor stroma from more than 300 prostate cancer patients." (PMID 20505768, 2010). "Similarly, GSTP1 was overexpressed in colon cancer but downregulated in prostate cancer, while PDGFRB showed an overexpression in liver cancer and downregulation in lung cancer." (PMID 39594421, 2024). "Our results support the clinical significance of PDGFRB in prostate cancer progression." (PMID 36809527, 2023). "This suggests that PDGFRA and PDGFRB might be effective therapeutic targets, and imatinib could be a potential candidate drug for S:E fusion-positive prostate cancer." (PMID 36579559, 2022). "In addition, imatinib, targeting PDGFRA and PDGFRB, was suggested as a potent actionable drug specific for S:E fusion-positive prostate cancer." (PMID 36579559, 2022). "Nearly all cells in both benign prostate stroma and prostate cancer stroma were PDGFRβ+." (PMID 33600062, 2021). "PDGFRB is a receptor tyrosine kinase (RTK) known to be expressed by stromal fibroblasts in several cancers and high stromal PDGFRB expression is associated with poor survival, e.g. in breast and prostate cancers." (PMID 33955203, 2021). "For example, in colorectal cancer, the expression of transforming growth factor α (TGFα) often leads to liver-only metastasis, whereas in prostate cancer, the expression of platelet-derived growth factor receptor beta (PDGFR-β) often leads to bone-only metastasis." (PMID 30103827, 2018).
prostate carcinoma (continued). "Moreover, siRNA-mediated knockdown of PDGFRα and PDGFRβ suppresses prostate cancer cell growth by the suppression of angiogenesis in a prostate cancer xenograft model." (PMID 28817103, 2017). "Furthermore, PDGF-DD and PDGFRβ are upregulated in most primary and metastatic prostate cancer cells." (PMID 28817103, 2017). "In these studies we report that high stromal expression of PDGFRβ and hyaluronan, both in the tumor stroma and in the stroma of the surrounding non-malignant tissue, was associated with a poor outcome of prostate cancer patients." (PMID 24505269, 2014). "Moreover, knock-down of PDGFRα, as well as PDGFRβ, by siRNA suppressed growth of prostate cancer cells in mice and suppressed tumor angiogenesis." (PMID 24359404, 2013). "Moreover, PDGFRβ mRNA expression was identified by microarray analyses as one of five mRNAs that predict prostate cancer recurrence, the other four being chromogranin A, HOXC6, IPTR3 and sialyltransferase-1." (PMID 24359404, 2013). "High tumor and non-malignant stroma PDGFRβ immunostaining was associated with an increased relative risk for prostate cancer specific death in a univariate Cox regression analysis." (PMID 20505768, 2010). "As a potent inhibitor against Abl, c-kit, PDGFRβ and, in particular, Src and EphA2, which have been shown to play important roles in prostatic tumorigenesis, dasatinib holds high promise as a potential treatment for prostate cancer." (PMID 18047674, 2007). "However, the role of methylation of PDGFRB in prostate cancer remains unclear, though it has been suggested that the PDGF methylation could regulate the activity of other oncogenic responses and act as a inducer for cellular proliferation in carcinogenesis." (PMID 24626295, 2014). "Interestingly, high levels of PDGFRβ in the stroma of tumor and non-malignant tissue were associated with shorter cancer specific survival in prostate cancer patients." (PMID 20505768, 2010). "PDGFRA and PDGFRB were targeted by multiple drugs, and imatinib, a BCR-ABL inhibitor, was identified to target both PDGFRA and PDGFRB in S:E fusion-positive prostate cancer." (PMID 36579559, 2022). "As ASPN expression was increased in cribriform prostate cancer, this collectively suggests that ASPN expression was induced in NT5E+ASPN− fibroblasts, TNC+ASPN− fibroblasts, and PDGFRβ+ASPN− fibroblasts in the cribriform tumor microenvironment." (PMID 33600062, 2021). "PDGFRA and PDGFRB are genes involved in the focal adhesion kinase (FAK)/PI3K-Akt signaling pathway, JAK-STAT pathway, and receptor tyrosine kinase/PDGF signaling pathway in S:E fusion-positive prostate cancer." (PMID 36579559, 2022). "The percentages of NT5E+, TNC+, and PDGFRβ+ cells did not significantly vary between stroma adjacent to benign prostate glands and prostate cancer." (PMID 33600062, 2021). "A prostate cancer related module was investigated (due to its significant enrichment on KEGG prostate cancer pathway), which has DEGs as PDGFRB, PDGFB, SNX2, EGFR and DECGs as (PDGFRA, PDGFRB), (SNX4, PDGFRB), (PDGFB, PDGFRA), (SNX2, PDGFRA), (PDGFRB, PIK3R2), (EGFR, PIK3R2), (EGFR, AREG)." (PMID 26070628, 2015). "In this study the prognostic significance of PDGFRβ in prostate cancer stroma, and in matched non-malignant tissue, was evaluated with immunohistochemistry." (PMID 20505768, 2010). "In addition, berberine inhibited prostate cancer cell invasion and migration by downregulating several EMT-related genes, such as platelet-derived growth factor receptor-beta (PDGFRB), collagen, type I, alpha 2 (COL1A2), and bone morphogenetic protein 7 (BMP7)." (PMID 35889396, 2022).
prostate carcinoma (continued). "Furthermore, NT5E, TNC, and PDGFRβ expression per positive cell was not significantly different between benign adjacent stromal cells and prostate cancer‐adjacent stromal cells." (PMID 33600062, 2021). "Finally, the “prostate cancer” pathway also includes DEGsSD that are relatively specific to the (human) prostate (SRD5A2, KLK2, NKX3-1 and CREB3L4), proto-oncogenes (EGFR, PDGFRA, PDGFRB, NRAS) and druggable candidates (PIK3CD, CTNNB1, PIK3CG, CDKN1A)." (PMID 34768937, 2021). "The “prostate cancer” pathway also comprises genes that are relatively specific to the (human) prostate (CREB3L4, KLK2, NKX3-1 and SRD5A2), proto-oncogenes (EGFR, NRAS, PDGFRA and PDGFRB), and druggable candidates (CDKN1A, CTNNB1, EGFR, NRAS, PDGFRA, PDGFRB, PIK3CD and PIK3CG)." (PMID 34768937, 2021). "In order to evaluate the significance of PDGFRβ in prostate cancer, a TMA containing matched non-malignant and tumor tissue from 377 prostate cancer patients with up to 25 year of follow- up was analyzed by PDGFRβ immunohistochemistry." (PMID 20505768, 2010).
hepatocellular carcinoma (49 papers, 2008 to 2026). A malignant tumor that arises from hepatocytes. "The PDGFRβ-targeted trimeric affibody conjugate [68Ga]Ga-DOTA-ZTRI has a highly specific binding affinity to tumor blood vessels of hepatocellular carcinoma." (PMID 37256321, 2023). "The specific point mutation PDGFRB N666S has not been described in hematopoietic malignancies, but has been observed in hepatocellular carcinomas (Cosmic Genomic Mutation ID: COSV55805999)." (PMID 33804823, 2021). "Sorafenib, approved by the FDA in 2007 as the first-line standard treatment for advanced hepatocellular carcinoma (HCC), targets critical tumor angiogenesis and proliferation pathways by inhibiting VEGFR1–3, PDGFRβ, and Raf-MEK-ERK signaling." (PMID 38893528, 2024). "Several potent PDGFRβ inhibitors, such as sunitinib, imatinib, nilotinib and sorafenib, have been developed for treating malignancies including chronic myelogenous leukemia (CML), renal cell carcinoma (RCC) and hepatocellular carcinoma (HCC)." (PMID 34360896, 2021).